SMAD3 (SMAD family member 3)
Diseases named in the same sentence as SMAD3 in open-access papers (continued):
Sharing a sentence is not in itself a finding about the gene and the disease.
melanoma (continued). "Direct activation of SMAD2 and SMAD3 by ALK3 has been demonstrated in BMP2-treated melanoma and pituitary gonadotrope cells, respectively." (PMID 29416020, 2018). "We transduced Amela as well as B16F10 melanoma cell lines with the lentivirus-based Smad3-reporter vector expressing green fluorescent protein (SBE-GFP)." (PMID 23173060, 2012). "Inhibition of the MAPK activation pathway in Amela tumor lines led to reduced Smad3 signaling, affected expression of EMT hallmark genes and inhibited proinflammatory cytokine Ccl2 gene expression and production by the melanoma cells." (PMID 23173060, 2012). "Riluzole-treated cells had increased linker phosphorylation of Smad2 at serines 245/250/255 in the five melanoma cell lines tested and of Smad3 at serine 204 in all but the 1205LU cell line." (PMID 23077590, 2012). "Interestingly, while the TGFβ effects on melanoma cancer stem cell maintenance require the Smad pathway, they also appear to be Smad3/4 specific and Smad2-independent." (PMID 38201651, 2024). "Altogether, these studies are consistent with our present findings in melanoma, suggesting that Smad3 may play a more prominent role in the mediation of the TGFβ tumor-suppressive effects compared to Smad2 in various models of solid tumors." (PMID 38201651, 2024). "We further show that these effects are mediated through the Smad pathway and that Smad3/4 gene silencing by means of CRISPR/Cas9 knockout (KO) could prevent the TGFβ anti-stemness effects in melanoma." (PMID 38201651, 2024). "Importantly, a subset of BRAF(V600E) melanoma patients (~20%) expressing the SMAD3‐signature was identified, suggesting that these tumors contained dedifferentiated melanoma cells with potential intrinsic resistance to BRAFi." (PMID 33724679, 2021). "To know if the combination (SMAD3i + BRAFi) could be broadly used to eradicate persister cells emerging in response to BRAFi treatment, we selected three melanoma cell lines in function of SMAD3 expression levels." (PMID 33724679, 2021). "In addition, we showed that gain‐of‐function of SMAD3 also promotes the three‐dimensional (3D) tumor spheroid invasion capability of melanoma cells." (PMID 33724679, 2021). "This SMAD3‐signature predicts resistance to both current melanoma therapies in different cohorts." (PMID 33724679, 2021). "Although this pathway is known to promote melanoma phenotype switching/dedifferentiation, to support melanoma growth and metastasis, little is known about the role of SMAD3 in melanoma biology and as a modulator of resistance to targeted therapy." (PMID 33724679, 2021). "Critically, chemical inhibition of SMAD3 may constitute amenable target for melanoma since it efficiently abrogates persister cells survival." (PMID 33724679, 2021). "This suggests that PSMD14 regulates melanoma growth through the SMAD3-p21 axis." (PMID 33154524, 2020). "Thus, our present study suggests that targeting PSMD14 can inhibit melanoma growth and migration through either SMAD3 accumulation or SLUG reduction, respectively." (PMID 33154524, 2020). "The TGF-β/Smad3 signaling pathway is also able to enhance Gli2 expression in melanoma." (PMID 33228057, 2020). "CSMD1 was recently shown to interact with SMAD3 in melanoma cells." (PMID 32701512, 2020). "The current study has demonstrated that rCTII might substantially stimulate the apoptosis pathways, especially the intrinsic pathway, inhibit the expression of mir-214 and MMP-3, and suppress the TGF-β pathway via down-regulating SMAD2 and SMAD3 in melanoma." (PMID 33167431, 2020). "The critical role of NK cell immunity in Smad3-dependent tumour microenvironment was further demonstrated by depleting NK cells from tumour-bearing Smad3−/− mice with a neutralizing anti-NK1.1 antibody to restore the aggressive progression of melanoma." (PMID 28262747, 2017).
melanoma (continued). "We previously demonstrated that the two pan-CDK/GSK3 inhibitors, flavopiridol and R547 could inhibit the constitutive linker phosphorylation of Smad2 and Smad3 in melanoma cell lines." (PMID 23077590, 2012). "These are correlated with constitutive Smad3 signaling in Amela tumors and melanoma cell lines." (PMID 23173060, 2012). "Our previous report suggested that Smad3 linker phosphorylation might contribute to the resistance to TGFβ-mediated cell growth inhibition in melanoma, by inhibiting the expression of p15 and p21." (PMID 23077590, 2012). "Moreover, using preclinical models of melanoma, we showed that the orthotopic transplantation of Smad3/4 CRISPR-KO melanoma cells led to a significant increase in tumor growth and lung metastatic nodule formation in vivo, further highlighting the strong tumor-suppressive role of TGFβ in melanoma." (PMID 38201651, 2024). "To address whether the canonical Smad pathway is involved in the mediation of the TGFβ effects on melanoma self-renewal, we generated specific Smad2, Smad3 and Smad4 knockout (KO) in two different melanoma cell lines, A375m and BLM, using CRISPR genomic editing." (PMID 38201651, 2024). "Besides, metformin inhibits melanoma development by repressing KAT5-regulated SMAD3 acetylation." (PMID 35392432, 2022). "Our results might suggest that these melanoma cells could be “addicted” to SMAD3 activity." (PMID 33724679, 2021). "We showed that SMAD3 inhibitor alone or in combination with BRAFi (Vem 5 μM) or BRAFi + MEKi (Cobi 1 μM) might be a promising treatment to reduce the amount of persister cells (melanoma)." (PMID 33724679, 2021). "CSMD (CUB and Sushi Multiple Domains 1) can interact with Smad3, confirming the role of CSDM1 as a tumor suppressor gene in melanoma cells." (PMID 39969704, 2025). "We discovered that TGFβ/Smad signaling inhibits melanosphere formation in multiple melanoma cell lines and reduces expression of the CD133+ cancer stem cell subpopulation in a Smad3-dependent manner." (PMID 38201651, 2024). "In this study, we focused on Smad3 and STAT6 in melanoma cells, and the phosphorylation of these two proteins was determined in western blotting assay accordingly." (PMID 39726752, 2024). "Using this reporter in a clonal B16F10 melanoma cell line, we observed heterogeneity in TGF-β/SMAD3-induced transcriptional response, distinguishing slow, fast, and non-responders." (PMID 35626109, 2022). "It had been reported that in melanoma, metformin suppressed phosphorylation of Smad3 by binding with the TGF-β1 extracellularly and meanwhile reduced the interactions of TβRI and Smad3 intracellularly." (PMID 35645830, 2022). "Taken together, TGF-β1/SMAD3 activates GLI1/2 via an SMO-independent mechanism to promote chemoresistance, enhance invasive potential, and promote the proliferation of melanoma." (PMID 34572373, 2021). "Our study has shown that the treatment of melanoma cells with rCTII can considerably reduce the expression levels of SMAD2 and SMAD3 genes, which can inhibit metastasis and tumor development." (PMID 33167431, 2020). "In recent studies, HF was found to inhibit phosphorylation of Smad3 via PI3K/Akt and MAPK/ERK pathways in muscle cells, and HF can block TGF-β signaling for inhibition of the establishment and progression of melanoma bone metastases." (PMID 26160839, 2015). "We have shown that riluzole induces the phosphorylation of the cluster of serines (245/250/255) in Smad2 and serine 204 in Smad3 via GSK3, in the majority of the melanoma cell lines analyzed." (PMID 23077590, 2012). "p-Smad3 is a key molecule in the TGF-β signaling pathway, and previous studies showed that TGF-β in the tumor microenvironment downregulates HLA class I expression on tumor cells of malignant melanoma." (PMID 40801643, 2025).
melanoma (continued). "Having shown that Smad3/4 gene silencing promote stemness and increases tumorsphere formation, and considering the prominent role played by cancer stem cells in promoting tumor formation, we next assessed the Smad3/4 CRISPR Kos in vivo, using preclinical models of melanoma tumor formation." (PMID 38201651, 2024). "Accordingly, C/EBPβ, SMAD3 and MITF are directly related to melanoma dedifferentiation." (PMID 39136013, 2024). "Further investigation revealed that TGF-β1/SMAD3 was directly involved in the noncanonical regulation of GLI1/2 activation in vemurafenib-resistant melanoma cell lines." (PMID 34572373, 2021). "Interestingly, we found that blocking Smad3 and Smad4 gene expression but not Smad2 significantly increased melanoma tumorsphere formation in both cell lines." (PMID 38201651, 2024). "In terms of acetylation, metformin inhibits SMAD3 phosphorylation and hinders the KAT5-SMAD3 interaction, which reduces KAT5-mediated K333 acetylation of SMAD3 to inhibit SMAD3 transcription and TRIB3 expression, thereby restoring autophagy and combating melanoma progression." (PMID 37344841, 2023). "For example, in melanoma, gain-of-function CRISPR screens have identified SMAD3, BIRC3, and SLC9A5 as main drivers of resistance to BRAF inhibitors, but only the upregulation of SMAD3 transcriptional activity induces a mesenchymal-like phenotype as well as BRAFi resistance." (PMID 36497228, 2022). "However, siRNA-mediated knockdown of SMAD3 did not produce alterations in miR-182 levels in melanoma cell lines." (PMID 28412746, 2017). "Combined with absence of p16/Arf tumor suppressors, the level of H-rasG12V may thus control key factors determining differentiation (Brn2, Mitf), EMT (JNK, Smad3, TGFβ signaling) and Ccl2 production (MAPK, JNK) during melanoma development as discussed hereafter." (PMID 23173060, 2012). "To assess whether pErk1/2 hyperactivation is required for the basal migration priming of high SMAD3 fibroblasts, we analysed basal Transwell migration in the presence of 100 nM Trametinib, a clinically approved inhibitor of MEK1/2 MAP kinases in NSCLC and melanoma that acts right upstream of Erk1/2." (PMID 36572730, 2023). "A total of 4 groups of NSG mice (7 mice/group) received a subcutaneous injection of the non-targeting control, Smad3 and Smad4 CRISPR KOs, generated in the A375m melanoma cell line." (PMID 38201651, 2024). "Mice lacking Smad3 were resistant to cancer metastasis with barely detectable LLC-luc cancer cells and a few melanoma nodules in the lung." (PMID 28262747, 2017). "We obtained the same results in C8161 and UACC930 human melanoma cell lines; SB431542 did not inhibit riluzole-induced Smad2 and Smad3 linker phosphorylation in these lines." (PMID 23077590, 2012). "In addition, in the UACC930 melanoma cell line, where the expression of GRM1 protein is not detectable, the induction of Smad2 and Smad3 linker phosphorylation in the presence of riluzole is comparable to that of the other melanoma cell lines that express GRM1." (PMID 23077590, 2012).
osteoarthritis (47 papers, 2011 to 2025). A noninflammatory degenerative joint disease occurring chiefly in older persons, characterized by degeneration of the articular cartilage, hypertrophy of bone at the margins and changes in the synovial membrane. "Patients with mutations in SMAD3 have a strong predisposition to osteoarthritis; cardiovascular involvement is mild." (PMID 37443678, 2023). "Among our three SMAD3-mutated families, early osteoarthritis, considered a hallmark of this subset of patients, was described only in one, although it segregated in the proband and his father." (PMID 31569402, 2019). "For example, the identification of a subset of LDS patients with pathogenic variants in SMAD3 displaying high frequency of osteoarthritis, prompted some authors to define the resulting phenotype as “aneurysms-osteoarthritis syndrome” or LDS type III." (PMID 31569402, 2019). "The presence of the suspicious SMAD3 variant, aortic aneurysm, and osteoarthritis suggested that LDS3 was the causal diagnosis." (PMID 31096651, 2019). "A growing body of evidence suggested that smad family member 3 gene rs12901499 polymorphism was associated with the risk of osteoarthritis." (PMID 29764993, 2018). "Several studies have been performed to investigate the association between SMAD3 gene polymorphism and osteoarthritis (OA), but the results were inconclusive." (PMID 30208919, 2018). "Enormous attention has been paid to the association between gene SNPs and risk of osteoarthritis, and SMAD3 SNP rs12901499 was studied by several researchers." (PMID 30208919, 2018). "In a previous study, SMAD3 was significantly associated with human osteoarthritis and upregulated in human osteoarthritic cartilage, though not due to DNA methylation in the promoter region." (PMID 30594196, 2018). "This meta-analysis confirmed that smad family member 3 gene rs12901499 polymorphism increased the risk of osteoarthritis." (PMID 29764993, 2018). "Some studies examining osteoarthritis in animal models showed that the TGF-β1/Smad3 signaling pathway was implicated in an initiation of cartilage injury via the downregulation of type II collagen." (PMID 29113082, 2017). "In this study, the presence of both aneurysms and osteoarthritis prompted us to perform SMAD3 screening in this family and find a causative mutation." (PMID 26221609, 2015). "Our finding expands the mutation spectrum of SMAD3 gene and further strengthens the connection between the presence of aneurysms-osteoarthritis phenotype and SMAD3 mutations, which facilitates the understanding of the genotype-phenotype correlation of AOS." (PMID 26221609, 2015). "We report on new findings in patients with SMAD3 gene mutations that extend the clinical spectrum beyond aortic dilatation and osteoarthritis which were previously reported." (PMID 24804794, 2014). "Mutations in the gene encoding Smad3 in autosomal dominant TAAD patients were recently associated with early onset osteoarthritis, defining a new entity: Aneurysms Osteoarthritis Syndrome (AOS)." (PMID 24804794, 2014). "Severe osteoarthritis and thoracic aortic aneurysms have recently been associated with mutations in the SMAD3 gene, but the full clinical spectrum is incompletely defined." (PMID 24804794, 2014). "SMAD3 gene mutations are associated with aortic dilatation and osteoarthritis, but also autoimmunity and peripheral neuropathy which mimics type II Charcot-Marie-Tooth." (PMID 24804794, 2014). "In fact, it was reported that Smad3 null mice show deregulated expression of MMP-9 while higher expression of this enzyme was detected in serum of osteoarthritis patients with Smad3 mutation." (PMID 24278749, 2012). "In addition, SMAD3 is implicated in abdominal aortic aneurysm, osteoarthritis, mesenchymal cell transition, and cardiac fibrosis." (PMID 34138687, 2021). "In addition, pathogenic SMAD3 variants have been found to be associated with TAA/D as well as premature osteoarthritis and skeletal abnormalities." (PMID 32597575, 2020).
osteoarthritis (continued). "Secondly, OA was considered as a multifactorial disease; however, the interactions between the gene and environment were not fully addressed in this meta-analysis, which may magnify the role of Smad3 polymorphism in osteoarthritis." (PMID 30208919, 2018). "In the present study, we assessed whether smad family member 3 gene rs12901499 polymorphism was associated with the risk of osteoarthritis by the meta-analysis." (PMID 29764993, 2018). "According to the previous studies, gene mutations of Smad3 could be associated with the pathogenesis of human osteoarthritis." (PMID 29113082, 2017). "–33 Similarly, rs12913547 is linked to the SMAD3 gene, which is a transcription modulator that has also been associated with aortic aneurysms and Loeys-Dietz syndrome (a syndrome characterized by increased arterial aneurysms and tortuosity, as well as osteoarthritis)." (PMID 40626804, 2025). "Interestingly, SMAD3 polymorphisms have recently been linked to the osteoarthritis risk." (PMID 32154675, 2020). "Based on the present analysis, we propose that patients harboring the G allele of SMAD rs12901499 polymorphism experience an increased susceptibility to OA in Caucasian, though the mechanism underlying the association between SMAD3 rs12901499 polymorphism and osteoarthritis is temporarily unknown." (PMID 30208919, 2018). "NFAT3 (nuclear factor of activated T-cells protein 3) and TGF-β/SMAD3 (mothers against decapentaplegic homolog 3) controlled miR-140 expression in osteoarthritis." (PMID 37359559, 2023). "In this study, we found that overexpression of miR-16-5p inhibited expression of Eda, Relt, Slc4a4, and Smad3. miR-16-5p has been detected in osteosarcoma, osteoarthritis, and bone fracture healing." (PMID 35401675, 2022). "In line with our data, despite early studies reported osteoarthritis in all SMAD3 patients, others noticed a lower incidence." (PMID 31569402, 2019). "Homozygous mutant mice in which Smad3 exon 8 is targeted (Smad3ex8/ex8) develop progressive degenerative cartilage resembling human osteoarthritis." (PMID 29392890, 2018). "As well as asporin other genes which belong to TGF-β signaling pathway are associated with osteoarthritis, including GFD5 and SMAD3." (PMID 29233086, 2017). "Recent studies show that mutations in Smad3 cause AOS, a new syndromic form of thoracic aortic aneurysms and dissections characterized by arterial aneurysms, early-onset osteoarthritis and mild craniofacial features." (PMID 23744273, 2013). "Smad3, a TGF-β receptor, when defective, causes early-onset osteoarthritis in humans." (PMID 41019141, 2025). "Pathogenic (P)/likely pathogenic (LP) SMAD3 variants cause Loeys-Dietz syndrome type 3 (LDS3), which is characterized by arterial aneurysms, dissections and tortuosity throughout the vascular system combined with osteoarthritis." (PMID 38538566, 2024). "Additionally, Smad3 knockout mice develop a degenerative joint disease resembling human OA and intervertebral disc degeneration." (PMID 26770254, 2015). "SMAD3 knock-out mice develop degenerative joint disease similar to human OA." (PMID 24852296, 2014). "More recently, mutations in the gene encoding SMAD3, which is an essential effector of TGFβ signaling, cause the newly described aneurysms-osteoarthritis syndrome (AOS), which is characterized by aortic aneurysms with early-onset osteoarthritis." (PMID 23744273, 2013). "Moreover, the Smad3−/− mice develop degenerative joint disease resembling human osteoarthritis, featuring an increased expression of Collagen X in the chondrocytes of synovial joints." (PMID 21297990, 2011). "Additionally, Smad3 knock‐out mice (Smad3−/−) show phenotypes similar to human osteoarthritis." (PMID 29392890, 2018). "This identified that genes with promoter sequences containing SMAD3 and IKZF1 binding motifs were over-represented in genes that were regulated during osteoarthritis." (PMID 37047586, 2023).